SMAD4 (SMAD family member 4)
Diseases named in the same sentence as SMAD4 in open-access papers (continued):
Sharing a sentence is not in itself a finding about the gene and the disease.
cancer (continued). "USP9x, due to its ability to regulate SMAD family member 4 (SMAD4) and apoptosis signal-regulating kinase 1 (ASK1), is also involved in regulating cancer-associated transforming growth factor- β (TGF-β) and mitogen-activated protein kinase (MAPK) signaling pathways." (PMID 31208103, 2019). "Furthermore, SPTBN1 expression is reduced in early stage CRC and that of Smad4 in advanced carcinomas, which indicates a key role for SPTBN1/Smad4/TGF-β signaling in the suppression of cancer progression." (PMID 31186638, 2019). "FHL1 acts in activation of the tumor suppressor gene p21 and repression of the oncogene c-myc through physically and functionally interacting with Smad2, Smad3 and Smad4 that are important regulators of cancer development and progression in a casein kinase 1δ-dependent manner." (PMID 30379883, 2018). "Besides the synthetic lethality seen in HR-deficient cancers with PARP inhibitors, collateral lethality was shown to play a role in SMAD4-mutated pancreatic cancers." (PMID 29329208, 2018). "Mono-ubiquitination of Smad4 occurs in the transcriptional activator complex and facilitates the turnover of Smad complexes at target genes, whereas poly-ubiquitination primarily occurs in unstable cancer mutants, leading to protein degradation." (PMID 29955155, 2018). "Same prognostic trends and positive correlation between the expression levels of FSTL1, BMP4, p-Smad1/5/8, and Smad4 indicates FSTL1 may regulate cancer progression through BMP4-p-Smad1/5/8-Smad4 signaling." (PMID 28852126, 2017). "In highly resistant spherical cancer cells, which results from enhanced self-renewal via cyclin D1 and cyclin D1-dependent activation of Smad2/3 and Smad4, inducing differentiation with Smad inhibitor is a critical tactic for turning resistant CSCs into therapy-sensitive cells." (PMID 28415588, 2017). "Additionally, epithelial expression of SMAD4 was decreased by nearly 50% in cancer specimens compared to adjacent normal tissue." (PMID 27270652, 2017). "SIRT7-mediated deacetylation of SMAD4 could be utilized as a TGF-β blocker if targeted therapy is necessary in appropriate cancer patients." (PMID 28827661, 2017). "Mechanistically, they show that TGFβ induces the expression of Sox4 in a Smad4-independent manner that then cooperates with the epithelial lineage determinant Kruppel like factor 5 (Klf5) to promote oncogenic growth in KrasG12D-driven cancers." (PMID 28649369, 2017). "Experiments have shown that SMAD4 inactivation promotes drug resistance in cancer." (PMID 27822437, 2016). "In conclusion, the present findings reveal that some mutations found in human cancers do not alter Smad4 function but rather inhibit TGF-β signaling by enhancing GSK3 phosphorylation of Smad4, which leads to its subsequent degradation." (PMID 27308538, 2016). "However, multiple studies have indicated that Smad4 has oncogenic functions in several kinds of human cancers." (PMID 26817584, 2016). "Moreover, in a custom-prepared tissue microarray (TMA) of PDAC tissues, strong SMAD4 immunoreactivity in the cancer cells correlates with enhanced microvessel density (MVD)." (PMID 26586478, 2016).
cancer (continued). "In conclusion, SMAD4 HD is associated with the constitutive activation of the ERK and Wnt/β-catenin signalling pathways, and favors the EGF-induced activation of multiple signalling pathways critical to cancer proliferation and invasion." (PMID 27655713, 2016). "Several cancers showed reduced response to TGF-β by presenting abnormalities in TGF-β receptors or Smad4, a mechanism by which cancer cells may escape from TGF-β-induced senescence." (PMID 26078812, 2015). "The present study also suggested that knockdown of Smad4 to inhibit the TGFβ signal during chemotherapy may sensitize cancer cells to chemotherapy, in part through the inhibition of MDR p-gp expression and reversal of the EMT process." (PMID 25684678, 2015). "Notably, the well-studied prognosis biomarker in cancers, SMAD family member 4 (SMAD4), regulated up to 1,382 optimal ceRNAs and was ranked 12th in the hub ceRNA list." (PMID 25917195, 2015). "Our findings suggest manipulating Smad4 functions might facilitate the control of infection, autoimmunity, and cancer." (PMID 26583325, 2015). "However, further study is needed on how SMAD4 driven N-cadherin expression influences the clinicopathological features of human cancers." (PMID 25264609, 2014). "Although these findings are based on a single model with Smad4 deficient CRC, further investigation of these cancer-driven host reactions in human CRC may lead to effective preventive measures against cancer metastasis." (PMID 25326065, 2014). "However, the potential prognostic value of the immunohistochemical detection of Smad4 in various types of cancer is inconsistent." (PMID 25333693, 2014). "In contrast, cancer cells later adapt to develop a resistance to TGF-β1-mediated growth inhibition by increasing expression of TGF-β1 antagonist, mutating the TGF-β1 receptor or inactivating the SMAD4 gene." (PMID 24625091, 2014). "Previous studies have suggested that Smad4 may regulate MMP7 expression in cancer, and we therefore examined the effect of transiently silencing Smad4 in oral squamous carcinoma cells by transfected siRNA." (PMID 25424420, 2014). "Thus, an effective meta-analysis to explore the prognostic value of Smad4 in various cancers is urgently needed." (PMID 25333693, 2014). "Similarly, cytoplasmic expression levels of Smad4 and p16 in cancer tissues were also negatively correlated with LNM (P = 0.032, P = 0.042, respectively)." (PMID 22860091, 2012). "Smad4 and p19 proteins were detected in all the clonal cancer cell lines examined." (PMID 22113502, 2011). "Together with GO function analysis, our results indicated that E2F may act as a major SMAD4 co-transcription factor partner in mediating cell proliferation in normal cells but lost in carcinoma cells." (PMID 21799915, 2011). "Loss of Smad4 in the carcinogenic process, in turn, is implicated in reduced or absent expression of laminin-332 in poorly differentiated carcinomas." (PMID 20307265, 2010). "WOX1 has been shown to induce Smad4-regulated promoter activation forinducing cancer cell death." (PMID 19918364, 2009). "Moreover, the marked difference of Smad4 expression is noted between carcinoma cells and surrounding residual normal ductal tissue from same specimen." (PMID 19943940, 2009). "However, resistance to TGF-β in cancer may occur through several mechanisms such as reduced expression of TβRI and/or TβRII, mutations or functional inactivation of TβRII, inactivating mutations in Smad2 and Smad4 and overexpression of inhibitory proteins including Smad7." (PMID 16251876, 2005).
cancer (continued). "Due to its high frequency in the Polish population, the variant alone may not confer the strong aggregation of cancer in family F6, but it may act as a modifier of another variant, such as the frameshift variant in SMAD4, also found in this family." (PMID 39654522, 2025). "This may be skewed by an early cancer diagnosis leading to SMAD4 analysis." (PMID 38627541, 2024). "Notably, cancers with high levels of this ECM signature not only exhibit activated TGFβ signaling in CAFs but also carry distinct genomic alterations, including BRAF and SMAD4 mutations." (PMID 38731846, 2024). "In cancer, only nonstop mutations in SMAD4 have been functionally characterized, while the impact of other nonstop mutations remain unknown." (PMID 39448564, 2024). "This suggests that SMAD4 may be a potential therapeutic target for cancer treatment." (PMID 38461536, 2024). "Also, it was proposed that the miR-324-3p/Smad4/Wnt signaling axis could be a therapeutic target to barricade cancer progression." (PMID 36978083, 2023). "Given the strong inflammatory phenotypes observed in epithelial Smad4‐deficient mice treated with DSS and the predisposing role of inflammation in cancer development, we extended our investigation to determine whether Smad4 plays a role in inflammation‐associated intestinal tumorigenesis." (PMID 37261975, 2023). "Thereafter, SMAD4 might have anti-cancer effects and sensitized CRC to irradiation treatment." (PMID 36694626, 2023). "Loss of SMAD4 is known to play a causal role in initiating gastrointestinal cancers, while in pancreatohepatobiliary cancers SMAD4 deficiency does not initiate tumorigenesis but acts as a promoter of a malignant process that was initiated by the other tumorigenic mechanisms." (PMID 35034624, 2022). "Therefore, we hypothesize that, like Smad4, Arl15 might play a similar dual-role in cancer progression." (PMID 35834310, 2022). "Notably, however, other studies suggested that SMAD4mut cancer cells might benefit from SMAD4-independent TGFβ/BMP receptor-driven signaling to undergo EMT-like changes, arguing for further complexity and plasticity among the routes to EMT in SMAD4mut tumors." (PMID 34857888, 2022). "In addition, String pathway interaction analysis identified six proteins (TGFBR2, TGFA, FGF21, SMAD4, TGFBR1, and FZD3) that were at the intersection of the cancer-associated pathways and, importantly, which were restored to their younger crosstalks by the rounds of TPE." (PMID 35999337, 2022). "Currently, more research is needed to characterize the relationship between Smad4, autophagy and cancer to determine if Smad4 genetic targeting in cancer cells could impede tumorigenesis by hindering both TGFβ and autophagy-dependent drivers of cancer." (PMID 34760883, 2021).
cancer (continued). "SMAD4 (DPC4) is related to the TGF-β signaling pathway, but some mutations result in abnormal signaling by TGF-β, a transforming growth factor receptor on the cell surface which can further increase the risk of cancer development by increasing the rate of cell growth and replication." (PMID 33803211, 2021). "Thus, the two suppressor genes PTEN and SMAD4 are linked through TGF-β pathway as they can mediate carcinogenesis, and their loss may attributes to cancer aggressiveness." (PMID 33825073, 2021). "Notably, CSCs bearing a somatic mutation in the “driver” gene SMAD family member 4 (SMAD4), may elicit antigen-specific T cell responses directed to both stemness and bulk cancer cells." (PMID 34572009, 2021). "Considering the strong links between invasiveness and EMT and the fundamental role of invasiveness in metastasis of cancer cells, our findings suggest that reducing these genes in our SDCs population after SMAD4 inhibition may offer new therapeutic approaches for RCC." (PMID 34012911, 2021). "TGF-β1, the most common isoform in human cancers, inhibits proliferation and induces apoptosis in various normal and premalignant human epithelial cells and its essential signaling intermediates, i.e., TβRII and Smad4, are therefore considered tumor suppressors." (PMID 33478130, 2021). "This may suggest different mechanisms and effects of SMAD4 inactivation in different cancer types." (PMID 33406242, 2021). "Therefore, the Smad4 reduction correlates the cancer progression." (PMID 34721577, 2021). "Moreover, overexpression of miR‐378 greatly decreased Smad4 mRNA level in cancer cells." (PMID 33372356, 2021). "Moreover, aberrant Smad4 expression has been observed in multiple diseases, particularly cancers." (PMID 33372356, 2021). "Significantly, the role of TGFβ in blocking cancer development also involves control of epithelial cell/tissue microenvironment interactions, as demonstrated by the development of epithelial cancers in mice with T-cell specific Smad4 deletion and fibroblast-specific TGFβRII deletion." (PMID 31480737, 2019). "Comprehensive mining of published in vitro genomics data pertaining to radiosensitivity revealed that simultaneous mutations in KRAS and SMAD4, which have not been described previously in uterine cervical cancer, are associated with cancer cell radioresistance." (PMID 30220971, 2018). "Testing the association between these signaling nodes and previously assessed surrogate markers of cancer risk using Pearson's correlation analysis revealed a significant positive correlation between ALDH+ and centrosome aberrations (P<0.05) and pATF2 and SMAD4 (P<0.05) (Sup." (PMID 28245431, 2017). "However, miR-27a and SMAD4 have also shown anti-cancer and oncogenic roles, respectively." (PMID 29065177, 2017). "Therefore, we propose that this combination could represent a novel therapeutic approach in PDAC patients whose cancers exhibit an angiogenesis gene signature and SMAD4-positive cancer cells." (PMID 26586478, 2016). "In addition, there may be limits to pursuing BARF1-specific effects on NFκB, miR-146a and SMAD4 in tissues, as cancer-related cellular proteins are likely controlled by intricate pathways in cancer tissues." (PMID 27438138, 2016). "Thus, we conducted a meta-analysis to evaluate the prognostic role of Smad4 in various cancers." (PMID 25333693, 2014). "Further more, we also found the SMAD4 mutant status associated with occupational exposure to pesticides, signifying that pesticides serves as the important risk factor in the development of CRC like other cancers, as has been previously reported in various studies." (PMID 20565773, 2010).
cancer (continued). "These seemingly contradictory results might be due, at least in part, to the distinct roles of Smad2, Smad3, and Smad4 in TGF-β signaling in the changing signaling context of cancer progression, resulting in altered target gene expression and ultimately different biological effects." (PMID 16438724, 2006). "While this canonical role of SMAD4 is well-established, emerging evidence suggests that SMAD4 also exhibits TGF-β-independent functions in diverse biological contexts, such as cancer, infectious diseases, and immune responses." (PMID 40856537, 2026). "Simultaneously, developing radiosensitizers tailored to genetic vulnerabilities (e.g., PARP inhibitors for SMAD4- or BRCA-mutant tumors, ATR inhibitors for ATM-overexpressing cancers) will expand therapeutic options." (PMID 40725389, 2025). "The interplay between SMAD4, C-MYC, and Cyclin D1 thus forms an essential signaling network that governs the proliferative capacity of cancer cells." (PMID 40224178, 2025). "We primarily attribute this to its demonstrated cytotoxic effects on cancer cell lines, anti-inflammatory characteristics, antimetastatic properties, capacity to induce apoptosis, and ability to inhibit the JNK/SMAD4/MMP2 signaling pathway." (PMID 38773159, 2024). "There was a greater difference in the expression of SMAD2, SMAD3, SMAD4, SMAD5, and SMAD9 between cancer and normal samples." (PMID 38514720, 2024). "Comparatively, TOPK emerges as a superior target for cancer therapy compared to other direct downstream molecules of ALK, including Smad4, STAT3, PI3K, and PLC-γ." (PMID 38397899, 2024). "These consequences confirmed that the regulatory effect of LINC00909 on pluripotency factors, cancer stemness and the activation of the MAPK/JNK pathway were dependent on the inhibition of SMAD4." (PMID 38504385, 2024). "Nonstop extension mutations in SMAD4 resulted in the translation of a hydrophobic degron sequence which led to strong proteasomal degradation of the extended protein and a loss-of-function phenotype, thus highlighting the functional relevance of nonstop mutations in cancer." (PMID 39448564, 2024). "SMAD4, also known as DPC4 (deleted in pancreatic cancer 4), is a crucial and central component of the TGF-β signaling pathway." (PMID 39335144, 2024). "Similar to the results of the 2D culture models, BI sup increased SMAD4/TGF-beta and regulated EMT-related genes in the 3D spheroid cancer models." (PMID 39113194, 2024). "The augmented activation of lipid metabolism pathways, potentially mediated by SMAD4 in CHODL+ NEO cells, underscores the complexity of cancer progression mechanisms." (PMID 38975339, 2024). "SMAD4 is the center of the TGF-β pathway and is considered an essential mediator of TGF-β signaling, which is overexpressed in various types of cancer." (PMID 38461536, 2024). "SMAD4 is the central mediator of TGF‐β signaling, and its function and signaling pathway abnormalities significantly contribute to the cancer genesis and progression." (PMID 37850692, 2024). "Previously reported focal CNAs in MSS primary cancers included single-copy and double-copy gains involving CCND1, ERBB2, MYC and KLF5, and deletions of ARID1A, SMAD4 and APC7,31." (PMID 39112709, 2024). "However, beyond SMAD4, no nonstop mutations in cancer have been functionally characterized and their general impact remains unknown." (PMID 39448564, 2024). "On the other hand, as indicated in Section 2, the paired expressions of uPAR and some specific cancer driver genes (i.e., MYC and SMAD4) can be utilized to further differentiate drug effects for precise medication to revert cancerous phenotypic change." (PMID 37895906, 2023).